LINC01465 (long independently transcribed non-coding RNA 1465)
Synonyms: C12orf61; FLJ25590
Gene: Long non-coding RNA gene on chromosome 12 (62,601,751 to 62,603,690, reverse strand). Ensembl gene ENSG00000221949.
Diseases named in the same sentence as LINC01465 in open-access papers:
LINC01465 is named in the same sentence as 1 disease in open-access papers, as found by Europe PMC text mining. Sharing a sentence is not in itself a finding about the gene and the disease. The quoted sentences say what the papers report.
cervical cancer (1 paper, 2023). A primary or metastatic malignant neoplasm involving the cervix. "Although experiments are required to determine the effect of LINC01465 on breast and cervical cancer, we suggest that spliceosomal mir-let-7i might inhibit the expression of LINC01465 (ENST00000408887.3) isoform." (PMID 37624034, 2023).